RNU6-1140P (RNA, U6 small nuclear 1140, pseudogene)
Gene: Small nuclear RNA gene on chromosome 2 (237,563,165 to 237,563,270, forward strand). Ensembl gene ENSG00000222449.
Homologues: Orthologues: chimpanzee U6 (99% identical), macaque U6 (87% identical), dog U6 (65% identical), mouse Gm23463 (62% identical). Paralogues in human: RNU6-1 (74% identical), RNU6-11P (74% identical), RNU6-16P (74% identical), RNU6-2 (74% identical), RNU6-25P (74% identical), RNU6-29P (74% identical), RNU6-33P (74% identical), RNU6-37P (74% identical), RNU6-38P (74% identical), RNU6-39P (74% identical), RNU6-3P (74% identical), RNU6-48P (74% identical), and 1283 more.